HDAC5 (histone deacetylase 5)
Diseases named in the same sentence as HDAC5 in open-access papers (continued):
Sharing a sentence is not in itself a finding about the gene and the disease.
cardiac hypertrophy (30 papers, 2012 to 2026). "Loss of either HDAC5 or HDAC9 led to cardiac hypertrophy in mice." (PMID 30721967, 2019). "In summary, Ang II can induce cardiac hypertrophy by triggering an HDAC5/HDAC6-dependent mechanism that can be reversed by NaB." (PMID 40710369, 2025). "Studies have found that Endog deficiency can promote cardiac hypertrophy through reactive oxygen species (ROS) accumulation, activation of the Akt and GSK3β signalling pathways, and HDAC4 and HDAC5 nuclear export." (PMID 40497340, 2025). "The knockout of Hdac5 or Hdac9 in cardiomyocytes increased the sensitivity of mice to adverse stimuli for cardiac hypertrophy, leading to cardiac hypertrophy and cardiomyopathy." (PMID 35958418, 2022). "Conclusively, Ang II can trigger an HDAC5/HDAC6-dependent cardiac hypertrophy mechanism, which can be reversed by NaB." (PMID 35958418, 2022). "For example, Ca2+ release from nuclear envelope activates CaMKII and promotes nuclear translocation of histone deacetylase 5 (HDAC5), initiating the cardiac hypertrophy." (PMID 34305595, 2021). "Next to cell-cycle genes, genes involved in cardiac hypertrophy such as Acta1 and Hdac5 were also expressed higher in cKO mice." (PMID 33917189, 2021). "An increase in histone deacetylase-5 (HDAC5) nuclear export, mediated by the protein kinase C (PKC)-dependent phosphorylation of HDAC5, has been shown to promote cardiac hypertrophy." (PMID 34307509, 2021). "In conclusion, we demonstrated that NaBu suppresses Ang II‐induced cardiac hypertrophy through the inhibition of COX2/PGE2 pathway in a HDAC5/HDAC6‐dependent manner." (PMID 31565858, 2019). "How HDAC5 contributes to pathophysiological processes following embryogenesis remains incompletely understood because most studies so far have focused on the regulatory role HDAC5 plays in cardiac hypertrophy by acting as a co-repressor for MEF2." (PMID 29212224, 2017). "Previous studies have identified PKD phosphorylation and induction of nuclear exclusion of HDAC5 as a mediator of persistent stress-induced cardiac hypertrophy." (PMID 23028574, 2012). "To unravel the effect of MI14 on the signaling pathways involved in the development of cardiac hypertrophy, we examined phosphorylation levels of the hypertrophy-associated kinases mTOR, ERK, PKD, the MEF2 adaptor HDAC5 and the Ca2+ dynamics regulator phospholamban (PLN)." (PMID 41596248, 2026). "This regulatory mechanism suggests that β‐AR may contribute to the protection against maladaptive myocardial hypertrophy and pathological myocardial remodelling by modulating HDAC5." (PMID 40497340, 2025). "Specially, a study demonstrates that sodium butyrate may function to inhibit HDAC5/HDAC6 to attenuate angiotensin (Ang) II-induced cardiac hypertrophy, suggesting HDAC5 may be a therapeutic target of cardiac hypertrophy." (PMID 37667300, 2023). "As a result, the HDAC5/1 complex induces a calcium overload process leading to cardiac hypertrophy." (PMID 35958418, 2022). "Of note, we also found TgGRK5 post-MI cardiomyocytes to have downregulated expression of HDAC5, which could partially contribute to the cardiac hypertrophy/dysfunction as shown by HCAD5KO mice during stress." (PMID 33560342, 2022). "However, HDAC5 was shown to play an integral role in cardiac development, suppression of oxidative stress, and heart hypertrophy, while HDAC7 maintained vascular integrity during early mouse heart development and participated in endothelial cell function." (PMID 32650632, 2020). "Thus, more detailed investigations are required regarding the role of HDAC5 during the development of cardiac hypertrophy and remodelling under different pathological settings and in different types of cells." (PMID 31565858, 2019). "The HDAC5-nuclear export pathway is strikingly reminiscent of that mediating cardiac hypertrophy in response to increasing cardiovascular stress, where HDAC nuclear export enables activation of MEF2 target genes required for hypertrophic growth of cardiac musculature." (PMID 31059522, 2019).
cardiac hypertrophy (continued). "Taken together, the controversy still exists about the role of HDAC5 in cardiac hypertrophy." (PMID 31565858, 2019). "To further confirm that NaBu may protect against Ang II‐induced cardiac hypertrophy through inhibition of HDAC5 and HDAC6, we carried out gene knockdown of HDAC5 and HDAC6 in cultured H9C2 cells via CRISPR/Cas9 strategy." (PMID 31565858, 2019). "Taken together, these results demonstrated that NaBu may suppress Ang II‐induced cardiac hypertrophy through COX2 signalling pathway by inhibiting the activation of HDAC5/HDAC6." (PMID 31565858, 2019). "HDAC4 and HDAC5 are signal-responsive repressors of cardiac hypertrophy." (PMID 31784580, 2019). "Also, an AKAP-Lbc-dependent signalosome mediates the activation and cytosolic release of activated protein kinase D (PKD), which has been shown to promote cardiac hypertrophy by facilitating the nuclear export of histone deacetylase 5 (HDAC5)." (PMID 29461511, 2018). "Furthermore, PKD1 has been proposed to facilitate cardiac hypertrophy through the phosphorylation of HDAC5 (histone deacetylase isoform 5) at Ser259 and Ser498." (PMID 24219103, 2014). "Nuclear HDAC5 associates with and represses the activity of MEF2 (myocyte enhancer factor 2) transcription factors, which drive the transcriptional reprogramming that precipitates pathological cardiac hypertrophy and remodelling." (PMID 24219103, 2014). "Of particular note is the role of PKD in cardiac hypertrophy where it regulates HDAC5." (PMID 23028574, 2012). "In addition, repression of HDAC5 phosphorylation and preventing HDAC5 nuclear export by YY1 overexpression significantly inhibited the increase in cell size and the re-expression of fetal genes associated with pathological cardiac hypertrophy." (PMID 37667300, 2023). "Also, HDAC5 nuclear export was believed to respond to hypertrophic stimuli, which results in pathologic hypertrophy, indicating that HDAC5 inhibition could be against cardiac hypertrophy." (PMID 37667300, 2023). "As expected, each of the phosphorylation levels of mTOR, ERK, TnI, PKD, HDAC5 and PLN was increased in PE-stimulated cardiomyocytes, supporting the use of PE stimulation as a suitable in vitro model of cardiac hypertrophy." (PMID 41596248, 2026). "The nuclear accumulation of HDAC4 and HDAC5 exerts inhibitory effects on the transcriptional activity of MEF2, thereby contributing to the pathogenesis of cardiac hypertrophy." (PMID 40497340, 2025). "Class II HDAC plays an anti‐hypertrophic role in cardiac hypertrophy, with research mainly focused on HDAC4 and HDAC5." (PMID 40497340, 2025). "Phosphorylation mutants of HDAC5 at serines 259 and 498 exhibit resistance to PKC-induced signaling and attenuated cardiac hypertrophy." (PMID 40710369, 2025). "Studies have shown that knockout of the HDAC5 and HDAC6 genes can block the COX2/PGE2 pathway in response to Ang II-induced cardiac hypertrophy." (PMID 40710369, 2025). "A-Kinase Anchoring Protein 13 (AKAP13) promotes downstream hypertrophic gene expression, mediated at least in part via HDAC5 phosphorylation and MEF2-mediated transcription in a transverse aortic constriction (TAC) model of cardiac hypertrophy." (PMID 36656640, 2023). "Our results demonstrated that HDAC5 was upregulated in both TAC mice and Ang II-treated H9C2 cells, suggesting its involvement in the development of cardiac hypertrophy and heart failure." (PMID 37667300, 2023). "Researchers also found that knocking down HDAC5 and HDAC6 via a gene-editing strategy dramatically blocked Ang II-induced hypertrophic responses in cardiac hypertrophy and fibrosis." (PMID 36263180, 2022). "However, over-activation of cardiac PKD1 in absence of high-fat diet causes cardiac hypertrophy through a mechanism involving phosphorylation of histone deacetylase-5 (HDAC5) and subsequent release of the transcription factor MEF2 to initiate hypertrophic programming." (PMID 33090289, 2021).
cardiac hypertrophy (continued). "In the heart, group IIa HDACs (HDAC4, HDAC5, HDAC7, and HDAC9) have been extensively studied and shown to be the endogenous inhibitors for cardiac hypertrophy." (PMID 30721967, 2019). "Class IIa HDACs, containing HDAC4, HDAC5, HDAC7, and HDAC9, play protective roles during cardiac hypertrophy." (PMID 31532577, 2019). "To further confirm the regulation of class II HDACs (HDAC5 and HDAC6) on the expression of COX2 and Ang II‐induced cardiac hypertrophy, we performed expression knockdown of HDAC5 and HDAC6 genes in H9C2 cells via CRISPR/Cas9 gene‐editing plasmids." (PMID 31565858, 2019). "For example, overexpression of HDAC4, HDAC5, and HDAC9 suppressed myocyte enhancer factor 2 mediated gene expression to prevent pathological stimuli-induced cardiac hypertrophy." (PMID 30721967, 2019). "One example of such regulation is GRK5-dependent phosphorylation of class II histone deacetylase 5 (HDAC5), which plays a role in pathological cardiac hypertrophy." (PMID 30837883, 2019). "The production of ANP showed the similar pattern as that of COX2, which further suggested that inhibition of HDAC5 and HDAC6 protects cardiomyocytes from Ang II‐induced cardiac hypertrophy." (PMID 31565858, 2019). "HDAC5 and HDAC9 have similar functions as endogenous inhibitors of cardiac hypertrophy in vivo." (PMID 40710369, 2025). "Furthermore, in addition to phosphorylating HDAC5 in the nucleus, GRK5 contributes to pathological cardiac hypertrophy by activating nuclear factor of activated T cells (NFAT) transcription factor in phosphorylation-independent manner via direct binding." (PMID 30837883, 2019). "Indeed, GRK5 phosphorylates histone deacetylase 5 (HDAC5), a repressor of myocyte enhancer factor 2 (MEF2), leading to nuclear export of HDAC5 and activation of MEF2 transcription activity, in cardiac hypertrophy." (PMID 27326393, 2016). "Accordingly, HDAC5-null mice develop exaggerated cardiac hypertrophy in response to pressure overload, whereas overexpression of HDAC5 suppresses MEF2-dependent transcription and agonist-dependent cardiac hypertrophy." (PMID 25514029, 2014). "In mouse models, the Class II HDACs HDAC9 and HDAC5 suppressed cardiac hypertrophy, and knockout mice lacking HDAC5 and HDAC9 showed spontaneous cardiac hypertrophy with age and in response to constitutive calcineurin activation or pressure overload due to aortic constriction." (PMID 39596076, 2024). "Furthermore, our findings suggest that HDAC5 may regulate MEF2A expression through the ERK/EGR1 signaling pathway, contributing to the progression of myocardial hypertrophy." (PMID 37667300, 2023). "However, the relationship between HDAC5, ERK/EGR1 signaling, and MEF2A in the context of cardiac hypertrophy remains unclear." (PMID 37667300, 2023).
glioma (23 papers, 2015 to 2025). A benign or malignant brain and spinal cord tumor that arises from glial cells (astrocytes, oligodendrocytes, ependymal cells). "HDAC4 and/or HDAC5 have been linked to tumorigenesis, tumor progression or chemoresistance in a variety of cancers, such as colon, urothelial, gastric, haematological, pancreatic, esophageal, or glioma." (PMID 36982651, 2023). "In glioma cell lines, cell proliferation was increased when HDAC5 was overexpressed and decreased with HDAC5 silencing." (PMID 38369747, 2024). "For example, histone deacetylase 5 (HDAC5) contributes to the development of chemoresistance in glioma cells." (PMID 37239035, 2023). "Univariate Cox regression indicated that high expression levels of HDAC1, HDAC3, HDAC7 and HDAC9 were associated with poor OS of glioma, and elevated expression levels of HDAC4, HDAC5, HDAC6 and HDAC11 were associated with a favorable prognosis of glioma." (PMID 35545840, 2022). "As well, knockdown of HDAC5 by siRNA technology in glioma cells suppressed the doxorubicin-induced EMT18." (PMID 33414476, 2021). "Notch1 signaling plays an important role in cancer cell proliferation; HDAC5 was shown to promote Notch1 expression in glioma cells, leading to increased glioma cell proliferation." (PMID 34178647, 2021). "HDAC5 is a histone deacetylase that enhances Notch1 expression in glioma cell lines promoting cell proliferation." (PMID 31628391, 2019). "For example, histone deacetylase 5 (HDAC5) has been shown to promote MT in gliomas and regulate therapy resistance." (PMID 28556516, 2017). "However, transcriptomic analyses in TCGA cohorts (grade 2/3 versus grade 4) and among our in-house glioma cultures showed that only 1 HDAC gene is consistently higher in IDHmut gliomas, HDAC5." (PMID 41066183, 2025). "Similar to HDAC4, HDAC5 was also found to be expressed at low levels in glioma tissue." (PMID 35545840, 2022). "Like HDAC4, HDAC5 has also been found to be down-expressed in glioma tissues." (PMID 36227941, 2022). "HDAC5 was also found to promote doxorubicin-induced EMT in glioma cells, which could account for chemoresistance in glioma." (PMID 34178647, 2021). "In addition, histone deacetylase 5 (HDAC5) has been identified to enhance glioma cell proliferation, and doxorubicin-treated glioma cells have been identified to have significantly increased HDAC5 levels." (PMID 31052435, 2019). "It was found that formononetin may enhance the therapeutic efficacy of doxorubicin in glioma cells by preventing EMT through inhibition of HDAC5." (PMID 30909474, 2019). "However, co-treatment with formononetin reduced the expression of HDAC5 in glioma cells." (PMID 31052435, 2019). "Ten glioma samples (5 IDH1 wildtype and 5 IDH1 mutant) were stained for various HDAC genes using internally validated antibodies (HDAC1, HDAC2, HDAC3, HDAC4, HDAC5, HDAC6 and HDAC7) and scored by a blinded neuropathologist (AK)." (PMID 37528157, 2023). "RNA-sequencing data from the public TCGA (The Cancer Genome Atlas) showed that HDAC4, HDAC5, HDAC6, HDAC8 and HDAC11 expression was significantly lowered in glioma (WHO grade II–IV) when compared to normal brain tissue." (PMID 37259375, 2023). "A model based on six HDAC genes (HDAC1, HDAC3, HDAC4, HDAC5, HDAC7, and HDAC9) can predict the overall survival of glioma patients well and these genes are potential therapeutic targets." (PMID 35545840, 2022). "Then, using six HDAC genes (HDAC1, HDAC3, HDAC4, HDAC5, HDAC7, and HDAC9), we established a prognostic model for glioma patients, and this prognostic model was validated in an independent cohort." (PMID 35545840, 2022).
glioma (continued). "Then, using six HDAC genes (HDAC1, HDAC3, HDAC4, HDAC5, HDAC7, and HDAC9), we established a prognostic model for glioma patients, and this prognostic model was validated in an independent cohort population." (PMID 35545840, 2022). "Differentially expressed HDAC family members were identified with significance in ONCOMINE, namely the upregulated HDAC1 and HDAC6, as well as the downregulated HDAC4, HDAC5, and HDAC11 in glioma." (PMID 34540896, 2021). "In contrast, under-expressed HDAC4, HDAC5, and HDAC11 ranking within the top 1% gene rank were observed in glioma." (PMID 34540896, 2021). "We also identified that HDAC1 and HDAC3expression levels were negatively correlated with survival time among gliomapatients, whereas the expression of HDAC4, HDAC5, HDAC6,HDAC11 and SIRT1 was positively correlated with survival time ofpatients with gliomas." (PMID 25791281, 2015). "Among all patients studied,the expression of HDAC1 and HDAC3 was inversely correlated withsurvival, whereas the expression of HDAC4, HDAC5, HDAC6,HDAC11 and SIRT1 was significantly and positively correlated withsurvival time of patients with gliomas." (PMID 25791281, 2015). "Because the HDAC5 enzyme is a class IIa HDAC that has very little influence on histone acetylation, elevated HDAC5 is unlikely to account for the enhanced HDACi-induced H3KAc observed in our IDHmut glioma cells." (PMID 41066183, 2025). "In the present study, HDAC5 expression was low in tumor cell lines and in glioma and normal tissues." (PMID 35359455, 2022). "We first performed the univariate cox regression and found that the elevated expressions of HDAC7, HDAC3, and HDAC1 were associated with poor prognosis while increased expressions of HDAC6, HDAC5, HDAC4, and HDAC11 were favorable for prognosis in low-grade glioma." (PMID 36227941, 2022). "However, HDAC5 upregulation was significantly correlated with tumor stage, poor OS, and DFS in all patients with glioma." (PMID 35359455, 2022). "Additionally, formononetin inhibited HDAC5 expression to attenuate doxorubicin-induced EMT, thereby promoting doxorubicin sensitivity in glioma cells." (PMID 34178647, 2021). "However, the expression levels of HDAC4 and HDAC5 were lower in the glioma patients than in the nontumor control groups." (PMID 35545840, 2022). "qPCR was adopted to detect the expression of HDAC1, HDAC3, HDAC4, HDAC5, HDAC7 and HDCA9 in nontumor and glioma tissues." (PMID 35545840, 2022).